ADAM15 (ADAM metallopeptidase domain 15)
Diseases named in the same sentence as ADAM15 in open-access papers (continued):
Sharing a sentence is not in itself a finding about the gene and the disease.
lung carcinoma (5 papers, 2021 to 2025). "However, the underlying ADAM15 functioning in lung cancer is still unclear." (PMID 35597804, 2022). "ADAM15 contains a consensus RGD site in its disintegrin domain, which can play a role in cell adhesion by binding to integrin αVβ3, and the colocalization of ADAM15 and αVβ3 integrin has been demonstrated in lung carcinomas." (PMID 35597804, 2022). "In order to evaluate the pipeline, we chose ADAM15 because of its known increased expression in breast and lung cancers (Schützet al., 2005) and well characterized alternative splicing events generating distinct transcript isoforms (Kleinoet al., 2007)." (PMID 33585928, 2021). "Additionally, proteins such as SHC1, MUC1, and ADAM15 display high betweenness centrality scores, indicating their importance as mediators in lung cancer progression." (PMID 40165937, 2025). "Moreover, ADAM15 was highly expressed in hepatocellular carcinoma and lung cancer tissues compared with corresponding noncancerous tissues based on the analysis of RT-qPCR, or Western blot and IHC." (PMID 40725774, 2025).
osteoarthritis (5 papers, 2005 to 2022). A noninflammatory degenerative joint disease occurring chiefly in older persons, characterized by degeneration of the articular cartilage, hypertrophy of bone at the margins and changes in the synovial membrane. "Although its substrate repertoire is quite limited, with only few proteins shown to be cleaved in vitro, ADAM15 is associated to development of age-related diseases, including osteoarthritis." (PMID 33673623, 2021). "Conversely, Adam15-null mice developed accelerated age-dependent osteoarthritis (OA), suggesting that ADAM15 has protective effects on the joint." (PMID 35736286, 2022).
melanoma (4 papers, 2015 to 2025). A malignant, usually aggressive tumor composed of atypical, neoplastic melanocytes. "The metalloproteinase ADAM15 is a multi-domain disintegrin protease that maps to a region of documented amplification associated with the metastatic progression of human cancers, including prostate, breast, ovarian, colon, and melanoma." (PMID 25693204, 2015). "Further, the inhibitory effects of NCK1-AS1 knockdown on cell proliferation and migration in melanoma were reversed by the depletion of miR-526b-5p and further counteracted by ADAM15 knockdown." (PMID 34247598, 2021). "In this study, NCK1-AS1/miR-526b-5p/ADAM15 axis was validated to modulate the proliferation and migration of melanoma cells." (PMID 34247598, 2021). "Altogether, NCK1-AS1 enhances cell proliferation and migration in melanoma by targeting miR-526b-5p/ADAM15 axis." (PMID 34247598, 2021). "NCK1-AS1 facilitates cell proliferation and migration in melanoma via targeting miR-526b-5p/ADAM15 axis." (PMID 34247598, 2021). "In conclusion, our study has certified that NCK1-AS1 boosts the progression of melanoma cells via miR-526b-5p/ADAM15 axis, offering insight into melanoma treatment." (PMID 34247598, 2021). "In short, our study demonstrated the facilitating role of NCK1-AS1 in melanoma and clarified the underlying mechanism of NCK1-AS1/miR-526b-5p/ADAM15 axis in melanoma, offering potential targets for melanoma treatment." (PMID 34247598, 2021). "In addition, in a model of melanoma angiogenesis, the tumors formed by implanted melanoma cells were significantly smaller in Adam15−/− mice than in wild-type controls." (PMID 41039222, 2025). "Herein, we investigated the ceRNA network related to ADAM15 in melanoma." (PMID 34247598, 2021). "Next, we carried out rescue experiments to examine whether NCK1-AS1 exerts its function in melanoma cells via regulating miR-526b-5p and ADAM15." (PMID 34247598, 2021). "Besides, miR-526b-5p binds to NCK1-AS1 in melanoma and ADAM15 was validated as its downstream target." (PMID 34247598, 2021). "In addition, ADAM15 has been proved to be essential in the metastasis of melanoma in previous studies." (PMID 34247598, 2021). "Likewise, wound healing and transwell migration assays showed that miR-526b-5p depletion offset the inhibited cell migration imposed by NCK1-AS1 knockdown, but ADAM15 knockdown hampered the migration of melanoma cells again." (PMID 34247598, 2021). "Thus, ADAM15 was verified as the downstream target of miR-526b-5p in melanoma." (PMID 34247598, 2021). "Next, RIP assay exhibited that NCK1-AS1, miR-526b-5p and ADAM15 were all significantly enriched in Ago2 antibody groups, suggesting the interplay among miR-526b-5p, NCK1-AS1 and ADAM15 in melanoma cells." (PMID 34247598, 2021). "However, the ceRNA mechanism of ADAM15 in melanoma was not discussed and studied." (PMID 34247598, 2021).
bladder cancers (3 papers, 2016 to 2025). "In the current study, we set out to validate the association of ADAM15 expression with advanced human bladder cancer and establish the functional participation of ADAM15 in the progression of this disease." (PMID 26930657, 2016). "Taken together, these results demonstrated that ADAM15 overexpression is closely associated with the local invasion and metastatic progression of human bladder cancer." (PMID 26930657, 2016). "In conclusion, we have found a novel association between ADAM15 expression and invasive bladder cancer and provide functional evidence for the role of ADAM15 in this disease." (PMID 26930657, 2016). "Third, bladder cancer progression is closely linked to angiogenesis, which may also be affected by the biological activity of ADAM15." (PMID 26930657, 2016). "The very high significant increase expression of ADAM15 in tumor (8.2 × 10−19) is in agreement with the up-regulation of ADAM15 previously reported in other cancers including breast, lung, prostate and bladder cancers." (PMID 33805340, 2021). "We began this study by surveying the OncomineTM (Compendia Bioscience, Ann Arbor, MI) gene expression database to assess DNA copy number and mRNA levels of ADAM15 in human bladder cancer arrays." (PMID 26930657, 2016). "Taken together, these results now suggest a critical role of ADAM15 and its metalloproteinase activity during the progression of human bladder cancer and potential therapeutic target." (PMID 26930657, 2016). "By further analyzing 3 independent transcriptome studies in OncomineTM (Sanchez, Lee and Blaveri), we found significant overexpression of ADAM15 mRNA in infiltrating bladder cancer compared to normal tissues." (PMID 26930657, 2016). "The knockdown of ADAM15 in a human xenograft model of bladder cancer inhibited tumor growth by 45% compared to controls." (PMID 26930657, 2016). "In this study, we utilized human bladder cancer tissues and cell lines to evaluate the expression and function of ADAM15 in the progression of human bladder cancer." (PMID 26930657, 2016). "Structural modeling of the catalytic domain led to the design of a novel ADAM15-specific sulfonamide inhibitor that demonstrated bioactivity and significantly reduced the viability of bladder cancer cells in vitro and in human bladder cancer xenografts." (PMID 26930657, 2016). "UM-UC-9 and UM-UC-6 bladder cancer cells expressed moderate levels of ADAM15 protein when normalized to GAPDH loading controls." (PMID 26930657, 2016). "Immunostaining of a bladder cancer tissue microarray was performed, showing specific focal overexpression of ADAM15 in the majority of the advanced (invasive and metastatic) bladder cancer specimens." (PMID 26930657, 2016). "Collectively, these data suggest that targeted inhibition of ADAM15 catalytic activity by adamastat reduces the viability of human bladder cancer cells." (PMID 26930657, 2016). "An analysis of 191 samples revealed that ADAM15 copy number is significantly elevated in advanced N stage (N1+) invasive bladder cancer compared to noninvasive (N0) disease." (PMID 26930657, 2016). "Second, E-cadherin, another substrate for ADAM15, has been found in the enzymatically processed form in both serum and urine samples from bladder cancer patients which also correlated with poor clinical outcome." (PMID 26930657, 2016). "Collectively these findings lend further support for ADAM15, and in particular its catalytic function, in the metastatic progression of human bladder cancer." (PMID 26930657, 2016). "This study also revealed that overexpression of ADAM15 correlated with tumor invasion and increased bladder cancer stage, suggesting a contributing role of ADAM15 in the progression of human bladder cancer." (PMID 26930657, 2016). "Using meta-analysis of various expression arrays, we previously demonstrated significant overexpression of ADAM15 in independent bladder cancer gene expression studies." (PMID 26930657, 2016).
bladder cancers (continued). "The significance of these observations to bladder cancer progression was validated by evaluation of ADAM15 protein expression in clinical specimens." (PMID 26930657, 2016). "Herein we have shown that the knockdown of ADAM15 lead to in vitro reduction of the migratory and invasive properties of human bladder cancer cells, including the ability to transmigrate though vascular endothelial monolayers." (PMID 26930657, 2016). "Moreover, in a xenograft model of human bladder cancer the growth of ADAM15 knockdown cells was inhibited by 45% compared with wild-type control cells." (PMID 41039222, 2025). "The biological and molecular profiles of bladder cancers suggested that overexpression and activation of ADAM15 may be relevant to the progression of this disease." (PMID 26930657, 2016). "To test whether the proteolytic function of ADAM15 is relevant in the regulation of bladder cancer microenvironment, we designed and synthesized adamastat, a selective inhibitor of ADAM15 metalloproteinase catalytic activity." (PMID 26930657, 2016). "Taken together, these data suggest a functional role of ADAM15 in the remodeling of the extracellular matrix, local invasion and interaction with the vascular endothelium during the metastatic progression of human bladder cancer." (PMID 26930657, 2016). "The present study examined ADAM15 copy number, mRNA levels and protein expression in clinical specimens of bladder cancer, which revealed significant correlations between amplification of the ADAM15 gene and overexpression of ADAM15 mRNA and protein in the progression of this disease." (PMID 26930657, 2016). "We investigated the endogenous expression of ADAM15 in two bladder cancer cell models and analyzed whether the reduction in ADAM15 expression inhibits bladder tumor cell motility." (PMID 26930657, 2016). "Although suggestive in other tumors, the association of ADAM15 with the instance or progression of human bladder cancer has not been previously investigated." (PMID 26930657, 2016). "Taken together, the results revealed an undescribed role of ADAM15 in the invasion of human bladder cancer and suggested that the ADAM15 catalytic domain may represent a viable therapeutic target in patients with advanced disease." (PMID 26930657, 2016). "However, further research is needed to assess the interactions of ADAM15 and sEcad in advanced bladder cancer." (PMID 26930657, 2016). "Preliminary examination of ADAM15 expression in tissue, cell lines and xenograft models of human cancer (histologically similar to the primary tumor) suggested its functional role in the progression of human bladder cancer." (PMID 26930657, 2016). "However, little was known about the expression levels of ADAM15 in human bladder cancer or how ADAM15 might functionally mediate the invasion and metastasis of bladder cancer cells." (PMID 26930657, 2016). "The molecular mechanism by which ADAM15 could support bladder cancer progression is unknown." (PMID 26930657, 2016). "However, the role of ADAM15 in the progression of bladder cancer had not been examined." (PMID 26930657, 2016).
hepatocellular carcinoma (3 papers, 2021 to 2025). A malignant tumor that arises from hepatocytes. "Besides, high expression of ADAM15 was an independent risk factor for the prognosis of hepatocellular carcinoma." (PMID 36157883, 2022). "However, the role of ADAM15 in hepatocellular carcinoma (HCC) remains unclear." (PMID 34426560, 2021).
inflammatory bowel disease (3 papers, 2015 to 2025). A spectrum of small and large bowel inflammatory diseases of unknown etiology. "ADAM15 has been shown to be upregulated in colon tissue from inflammatory bowel disease patients compared with healthy controls." (PMID 25743184, 2015). "ADAM15 is expressed also in intestinal epithelial cells, where it plays a major role in intestinal inflammation, epithelial wound healing and mucosal remodeling in inflammatory bowel disease." (PMID 41039222, 2025).
metastatic disease (3 papers, 2016 to 2025). "The ADAM15 immuno-positivity increased in advanced stage and was significantly greater as the tumors progressed from noninvasive to invasive and metastatic disease." (PMID 26930657, 2016). "Moreover, ADAM15 cDNA and protein levels were significantly increased in prostate tumor tissue and correlated with metastatic disease progression." (PMID 40725774, 2025).
non-small cell lung carcinoma (3 papers, 2022 to 2025). A group of at least three distinct histological types of lung cancer, including non-small cell squamous cell carcinoma, adenocarcinoma, and large cell carcinoma. "Other authors have analyzed the association of ADAM15 expression with the clinicopathological characteristics of patients with non-small cell lung cancer." (PMID 40725774, 2025). "In this regard, the interaction of ADAM15 with integrin αvβ3 has been shown to influence non-small-cell lung cancer (NSCLC) proliferation and metastasis through focal adhesion kinase (FAK) activation and signaling." (PMID 41039222, 2025). "The authors confirmed that ADAM15 served a crucial role in the progress of HCC and non-small cell lung cancer." (PMID 40725774, 2025).
Alzheimer disease (2 papers, 2023 to 2025). A progressive, neurodegenerative disease characterized by loss of function and death of nerve cells in several areas of the brain leading to loss of cognitive function such as memory and language. "Mendelian randomization analyses suggested causal roles for several proteins, for example, ApoE, CD33, and GRN in Alzheimer's disease, MMP‐10 in preclinical Alzheimer's disease, SIGLEC9 in amyotrophic lateral sclerosis, and CD38, GPNMB, and ADAM15 in Parkinson's disease." (PMID 36504281, 2023).
amyotrophic lateral sclerosis (2 papers, 2023 to 2025). Amyotrophic lateral sclerosis (ALS) is a neurodegenerative disease characterized by progressive muscular paralysis reflecting degeneration of motor neurons in the primary motor cortex, corticospinal tracts, brainstem and spinal cord. "It directly binds to and regulates the function of caspase-8, of proteasome-mediated RIPK1 stability in amyotrophic lateral sclerosis, as well as vesicle trafficking and autophagy, and therefore represents a promising regulator of vesicular ADAM15." (PMID 41340056, 2025).
Arthritis (2 papers, 2017 to 2021). Inflammation of a joint. "Our elucidation of the critical impact of ADAM15 on the orchestration of mechanoinflammation in SF suggests its potential as a target for therapeutic intervention, which is supported by data on the amelioration of murine collagen-induced arthritis through treatment with ADAM15-specific siRNA." (PMID 34685689, 2021). "Similar to ADAM10, knockdown of ADAM15 results in suppressed migration and invasion of FLS and silencing of ADAM15 in a rat model of CIA reduced the arthritis score and the extent of joint damage." (PMID 28260841, 2017).
autoimmune disease (2 papers, 2014 to 2019). A disorder resulting from loss of function or tissue destruction of an organ or multiple organs, arising from humoral or cellular immune responses of the individual to their own tissue constituents. "ADAM15 is a pro-inflammatory molecule with its expression and function upregulated in various tissues during the development of metastatic cancer and autoimmune diseases." (PMID 25333931, 2014).
bladder tumor (2 papers, 2016 to 2025). "Immunostaining of a bladder tumor tissue array designed to evaluate disease progression revealed increased ADAM15 immunoreactivity associated with increasing cancer stage and exhibited significantly stronger staining in metastatic samples." (PMID 26930657, 2016). "In these experiments, both ADAM15 knockdown or inhibition of its catalytic activity by adamastat proved to reduce bladder tumor growth in immuno-deficient mice; however, a full histopathological assessment as to whether the reduced tumor size is due to cytotoxicity remains to be evaluated." (PMID 26930657, 2016). "The knockdown of ADAM15 mRNA expression significantly inhibited bladder tumor cell migration and reduced the invasive capacity of bladder tumor cells through MatrigelTM and monolayers of vascular endothelium." (PMID 26930657, 2016).
colorectal cancer (2 papers, 2025). A primary or metastatic malignant neoplasm that affects the colon or rectum. "These authors found a reduced expression of ADAM15 (both at protein and mRNA levels) without promoter methylation in 36% of colorectal carcinomas, which was associated with histologically poorly differentiated carcinomas." (PMID 41039222, 2025).
glioma (2 papers, 2024 to 2025). A benign or malignant brain and spinal cord tumor that arises from glial cells (astrocytes, oligodendrocytes, ependymal cells). "Remarkably, both ADAM10 G342E (score = −0,81) and ADAM15 N792S (score −1,1) missense pathogenic mutation were associated to low grade glioma, methylated MGMT promoter status and mutant IDH status, which correspond to a positive prognosis in glioma patients." (PMID 38272115, 2024). "While mutations in EFEMP2, ADAM10, SERPINH1, ADAM15, GAS6 and TNXB were detected only in patients with glioma grade 3, mutations in LTBP2, DCN, CRELD1 and HAPLN3 were observed only in patients with glioma grade 4, GBM." (PMID 38272115, 2024).
liver cancer (2 papers, 2021 to 2024). An epithelial or non-epithelial malignant neoplasm that arises from the liver. "We analyzed the mRNA expression data of LIHC in TCGA and found that ADAM15 was highly expressed in liver cancer tissues than that in the matched normal tissues." (PMID 34426560, 2021). "ADAM15 knockdown promoted apoptosis and suppressed proliferation, migration and invasion of liver cancer cells." (PMID 34426560, 2021). "Notably, the downregulation of ADAM15 promotes apoptosis in liver cancer cells and hampers tumor cell proliferation, migration, and invasion." (PMID 39346916, 2024). "Our study corroborates these findings, as we identified abnormal overexpression of ADAM9, ADAM10, ADAM15, and ADAM17 in liver cancer tissues through both GEPIA website analysis and PCR experiments." (PMID 39346916, 2024). "The results confirmed that ADAM9, ADAM10, ADAM15, and ADAM17 exhibited an upregulation trend in at least one liver cancer cell line, consistent with our earlier predictions." (PMID 39346916, 2024).
lung diseases (2 papers, 2020 to 2025). "ADAM15 has not been studied previously in COPD and little is known about its expression or activities in health or other lung diseases." (PMID 32677970, 2020).
Obesity (2 papers, 2019 to 2023). Accumulation of substantial excess body fat. "Likewise, DHA acted on genes like BMPER3, NFATC4 and ADAM15, belonging to categories deregulated under obesity adding further evidence for a potential role of this PUFA in attenuating obesity-related AT inflammation." (PMID 30838002, 2019).
pancreatic cancer (2 papers, 2019 to 2025). "ADAM12 or ADAM15 interacts with SH3 domain of SRC, resulting in activation of the SRC cascade in pancreatic cancer cells." (PMID 31888763, 2019).